BDNF (brain derived neurotrophic factor)
Diseases named in the same sentence as BDNF in open-access papers (continued):
Sharing a sentence is not in itself a finding about the gene and the disease.
lymph node metastasis (8 papers, 2010 to 2025). "Univariate analysis revealed that low BDNF methylation was associated with lymph node metastasis and a shorter disease-free survival." (PMID 25908946, 2015). "Additionally, research indicates that high BDNF/TrkB expression in NSCLC is associated with lymph node metastasis and vascular invasion." (PMID 40654575, 2025). "In addition, univariate analysis revealed that low BDNF methylation was associated with lymph node metastasis and shorter disease-free survival." (PMID 25908946, 2015). "Low BDNF methylation levels were also associated with lymph node metastases (P = 0.035)." (PMID 25908946, 2015). "Multivariate Cox regression survival analysis indicated that tumor maximum diameter of 20 mm or more, lymph-node metastasis, and invasion to surrounding tissue, followed by BDNF-positive expression or BMPR1A-negative expression were the most significant predictors of short DSS." (PMID 23531103, 2013). "We also found a significant correlation between higher BDNF expression and lymph node metastasis." (PMID 21999199, 2011). "A high level of expression of neurotrophic factors including BDNF and NGF correlates closely and positively with a high FIGO stage, lymph node metastasis, the growth of neurons, and poor long-term outcomes in OC." (PMID 37799274, 2023). "Moreover, a significant difference of BDNF, not TrkB expression was detected between variously differentiated HCCs (p = 0.036), and between HCCs with or without lymph node metastasis (p = 0.016)." (PMID 21999199, 2011).
osteosarcoma (8 papers, 2012 to 2025). A usually aggressive malignant bone-forming mesenchymal neoplasm, predominantly affecting adolescents and young adults. "Core features of NGF/TrkA and BDNF/TrkB signaling relevant to osteosarcoma biology and antitumor immunity." (PMID 41567220, 2025). "NGF/TrkA and BDNF/TrkB constitute actionable determinants of osteosarcoma progression and antitumor immunity." (PMID 41567220, 2025). "Osteosarcoma cells appear to reuse this programme: exogenous BDNF enhances clonogenicity, mitigates chemotherapy-induced apoptosis and promotes a spindle-shaped, vimentin-positive phenotype, features that collectively align with heightened metastatic risk." (PMID 41142827, 2025). "Among these, nerve growth factor (NGF) binding to tropomyosin receptor kinase A (TrkA) and brain-derived neurotrophic factor (BDNF) binding to TrkB represent two conserved signaling axes with direct relevance to osteosarcoma biology and its immune milieu." (PMID 41567220, 2025). "Therapeutic interventions targeting NGF/BDNF–Trk and neural co−regulatory pathways in osteosarcoma immunity: targets, mechanistic rationale, pharmacodynamic biomarkers, and combination strategies." (PMID 41383615, 2025). "The purpose of this article is to define NGF/BDNF as shapers of the osteosarcoma immune microenvironment and to delineate biomarker−guided therapeutic opportunities for clinical testing." (PMID 41383615, 2025). "The purpose of this review is to synthesize current evidence and propose a translational roadmap for targeting NGF/TrkA and BDNF/TrkB to remodel antitumor immunity in osteosarcoma." (PMID 41567220, 2025). "This mini review synthesizes current knowledge on NGF/TrkA and BDNF/TrkB axes in osteosarcoma with emphasis on neurotrophin-driven remodeling of antitumor immunity." (PMID 41567220, 2025). "These tumor-cell-intrinsic and immunomodulatory activities place the BDNF/TrkB axis as a candidate determinant of antitumor immune quality in osteosarcoma." (PMID 41567220, 2025). "The collective evidence positions NGF/TrkA and BDNF/TrkB as context-dependent organizers of osteosarcoma biology and its immune microenvironment." (PMID 41567220, 2025). "Converging mechanistic and translational observations support a model in which NGF/BDNF signaling shapes osteosarcoma biology at three interdependent levels: tumor cells, the vascular–stromal interface, and immune effectors." (PMID 41383615, 2025). "In this review, we summarized NGF/BDNF expression and receptor activity in osteosarcoma and conducted a translational, efficacy− and safety−oriented appraisal of tissue/biofluid biomarker readouts and drugging opportunities targeting neurotrophin and co−regulatory neural circuits." (PMID 41383615, 2025). "Mechanistic map of NGF/TrkA and BDNF/TrkB effects on immune and stromal components in osteosarcoma." (PMID 41567220, 2025). "Mechanistic map of NGF/BDNF signaling nodes relevant to osteosarcoma immunity." (PMID 41383615, 2025). "Moreover, the knockout of Circ_0000006 potentiates the effects of doxorubicin on osteosarcoma-repressed cell proliferation, migration, and invasion via the miR-646/BDNF pathway." (PMID 39247831, 2024). "Furthermore, activation of the BDNF–TrkB axis has been correlated with enhanced proliferation, resistance to apoptosis, and invasive behaviour in multiple malignancies, and similar molecular programmes have been described in experimental osteosarcoma systems." (PMID 41142827, 2025). "Taken together, NGF-TrkA, BDNF-TrkB and GDNF–RET circuits endow osteosarcoma cells with proliferative, anti-apoptotic and pro-metastatic properties." (PMID 41142827, 2025). "NGF–TrkA shows highest expression; BDNF–TrkB and GDNF–GFRα/RET are variable, whereas NT−3/TrkC is low in osteosarcoma but prominent in other bone sarcomas, hence our emphasis." (PMID 41142827, 2025). "In osteosarcoma samples, NGF and TrkA mRNA expression levels were higher than those of BDNF, NT-3, NT-4, TrkB, or TrkC." (PMID 38816365, 2024).
osteosarcoma (continued). "We also observed in the gene expression analysis that genes that are bonafide targets of YAP such as BDNF, DYN3, CTGF LOX and CYR61 have reduced expression upon TZD treatment only in osteosarcoma cells." (PMID 27528232, 2016).
overactive bladder (8 papers, 2015 to 2023). Symptom of overactive detrusor muscle of the urinary bladder that contracts with abnormally high frequency and urgency. "Urinary BDNF has been proven to be an optimal marker to detect overactive bladder diseases, as reported in children with enuresis." (PMID 38268968, 2023). "We designed this experiment to elucidate the relationship between the expression of brain derived-neurotrophic factor (BDNF), the expression of granulocyte-colony stimulating factor (G-CSF), and the development of overactive bladder (OAB)." (PMID 25951823, 2015). "BDNF may be induced due to nerve damage and participates in chronic pain onset, while some authors claim it may become a biomarker of an overactive bladder." (PMID 34072606, 2021). "Concentrations of brain-derived neurotrophic factor (BDNF) and its precursor (proBDNF) were measured in the urine of a cohort of aging female patients with overactive bladder disease (OAB)." (PMID 37367881, 2023). "Both antimuscarinic agents and botulinum toxin, similarly to asiatic acid, diminish the urinary levels of BDNF and NGF in patients with bladder overactivity." (PMID 33584259, 2020). "Furthermore, urinary BDNF and NGF were examined as potential biomarkers for overactive bladder (OAB)." (PMID 35801157, 2022).
pneumococcal meningitis (8 papers, 2013 to 2025). An acute purulent infection of the meninges and subarachnoid space caused by Streptococcus pneumoniae, most prevalent in children and adults over the age of 60. "Notably, previous studies have shown that the functional cognitive deficit, such as an impairment in learning and memory, caused by experimental pneumococcal meningitis in adult rodents, is exacerbated by the selective loss of the BDNF in infected conditional knock-out mice." (PMID 37371040, 2023). "In this study, we investigated the effects of BDNF-related signaling on the inflammatory response and hippocampal apoptosis in experimental models of pneumococcal meningitis." (PMID 28778220, 2017). "Additionally, BDNF pretreatment suppresses their levels in the cortex and hippocampus in a model of pneumococcal meningitis." (PMID 40564462, 2025). "Our previous studies showed that BDNF adjunctive treatment with antibiotics for 7 d could rescue cortical and hippocampal neurons in a rat model of pneumococcal meningitis." (PMID 32676082, 2020). "Recent studies have shown that brain-derived neurotrophic factor (BDNF) mediates anti-inflammatory and neuroprotective effects in CNS diseases; however, the distinct contribution of BDNF to pneumococcal meningitis (PM) remains unknown." (PMID 32676082, 2020). "Since treatment with exogenous BDNF results in the reduction of various forms of cell death in experimental pneumococcal meningitis, one can speculate that the up-regulated expression level of BDNF in vitamin B6-treated animals plays an important role in diminishing hippocampal apoptosis." (PMID 23977941, 2013). "In our experiment, we observed that lithium prevented memory impairment and increased hippocampal BDNF, NGF, and GDNF neurotrophin expression in experimental pneumococcal meningitis." (PMID 29200666, 2017). "Among those drugs, we studied the effect of tamoxifen as well as lithium on BDNF, GDNF, and NGF expression in the hippocampus and on behavior tasks in an experimental model of pneumococcal meningitis in rats." (PMID 29200666, 2017). "The aim of this study was to investigate the effects of lithium on brain-derived neurotrophic factor (BDNF), nerve growth factor (NGF), and glial cell line-derived neurotrophic factor (GDNF) expression in the hippocampus and on memory in experimental pneumococcal meningitis." (PMID 29200666, 2017). "Hence, the aim of this study was to investigate the effects of lithium and tamoxifen on BDNF, GDNF, and NGF expression in the hippocampus and on behavior tasks in an experimental model of pneumococcal meningitis." (PMID 29200666, 2017).
polycystic ovary syndrome (8 papers, 2012 to 2026). A disorder that manifests as multiple cysts on the ovaries. "One study did report on increased BDNF levels in women suffering from polycystic ovary syndrome (PCOS), which is characterized among others by the presence of hyperandrogenemia." (PMID 26753091, 2016). "Additionally, certain studies have found that hyperandrogenemia in women with PCOS could correlate to increased levels of the BDNF." (PMID 31281833, 2019).
airway hyperresponsiveness (7 papers, 2006 to 2025). "Some studies have shown that, in patients not receiving inhaled corticosteroid treatment, elevated platelet brain-derived neurotrophic factor concentrations are associated with airflow limitation and airway hyperresponsiveness." (PMID 40182327, 2025). "miR-10a mediates airway hyperresponsiveness by suppresses cell proliferation of airway smooth muscle, via targeting BDNF in asthmatic rats." (PMID 32016112, 2020). "These clinical data confirmed findings from animal models of allergic asthma, which showed a crucial role of BDNF in the pathogenesis of airway hyperresponsiveness and airway obstruction." (PMID 23245944, 2012). "Increased BDNF concentrations and increased airway hyperresponsiveness were both reduced after concomitant therapy with fluticasone confirming previous data showing a suppression of BDNF production by corticosteroids." (PMID 23245944, 2012). "In patients with allergic asthma, serum and platelet concentrations of BDNF are elevated as compared with healthy controls, and correlate with airway obstruction and airway hyperresponsiveness." (PMID 23245944, 2012). "BDNF induces neuronal hyperreactivity leading to airway hyperresponsiveness and cough and increases the number and function of airway smooth muscle cells." (PMID 23245944, 2012). "The neurotrophins, including nerve growth factor (NGF), brain-derived neurotrophic factor (BDNF) and neurotrophin-3 (NT-3), have been shown to be elevated during airway inflammation and evoke airway hyperresponsiveness." (PMID 16441896, 2006). "In conclusion, the present study shows that BDNF upregulates a number of mechanisms important in airway contractility which, in combination with enhancement of ASM cell proliferation and cytokine effects can substantially influence airway hyperresponsiveness." (PMID 22952960, 2012). "It was previously shown that serum and platelet concentrations of BDNF (but not TGF-β1) are elevated in patients with mild to moderate allergic asthma, correlating with airway obstruction and airway hyperresponsiveness." (PMID 23245944, 2012).
anemia (7 papers, 2013 to 2024). A reduction in the number of red blood cells, the amount of hemoglobin, and/or the volume of packed red blood cells. "Lower cord blood BDNF concentration with maternal anemia has been reported previously and was associated with decreased hippocampal volume at birth." (PMID 38613125, 2024). "In another study, 6-week supplementation of curcumin (500 mg/day) with iron has been reported to cause 35% improvement in BDNF, despite the previous reports that curcumin intake in mice caused chelation of iron in vivo and developed significant anemia." (PMID 39081970, 2023). "For example, the inverse relationships of cord ferritin and maternal anemia with exosomal BDNF in female neonates suggest additional roles for circulating BDNF." (PMID 31623079, 2019).
autoimmune disease (7 papers, 2010 to 2024). A disorder resulting from loss of function or tissue destruction of an organ or multiple organs, arising from humoral or cellular immune responses of the individual to their own tissue constituents. "BDNF not only affects autoimmune diseases but also contributes to protective immune responses by regulating T cell responses." (PMID 38721229, 2024). "Local production of BDNF as well as the expression of its high affinity receptor TrkB is also enhanced in synovitis in autoimmune disease." (PMID 21085492, 2010). "Although pro-inflammatory cytokines play a role in promoting NT secretion, other mechanisms are probably involved in NGF and BDNF release in autoimmune diseases." (PMID 21085492, 2010). "The mechanism of Jia-Wei-Xiao-Yao-San (JWXYS) in autoimmune disease was observed to increase synaptic plasticity and decrease the levels of inflammatory markers by upregulating the expression of hippocampal brain-derived neurotrophic factor (BDNF)." (PMID 34651000, 2021). "Blueberry may improve depression-induced autoimmunity disorder and reduce gastrointestinal infection by affecting BDNF level via miR-155." (PMID 29230173, 2017). "Indeed, growing evidence suggests that NGF, BDNF, and NT-3 participate in inflammatory responses, including the modulating and regulating immune function in inflammatory and autoimmune diseases." (PMID 24223945, 2013). "However, data concerning the influence of corticosteroid and/or immunosuppressive drugs on systemic levels of NGF and BDNF in autoimmune diseases are contradictory." (PMID 21085492, 2010). "Therefore, BDNF appears to play a crucial role in the pathophysiology of autoimmune diseases." (PMID 38721229, 2024). "Considering that no reported experimental data support the involvement of NT4/5 in B and T cell activation or autoimmune disease, this study mainly focused on the relationship between serum levels, B-lymphocyte expression of NGF, BDNF and NT-3, and SLE activity." (PMID 24223945, 2013). "Accumulating evidences suggest that NTs, especially Nerve Growth Factor (NGF) and Brain-Derived Neurotrophic Factor (BDNF), participate in inflammatory responses, including the modulation and regulation of immune functions in inflammatory and autoimmune diseases." (PMID 21085492, 2010). "A combination of four different proteins: BDNF (Brain Derived Neurotrophic Factor), I-TAC/CXCL11, soluble (s) CD163 and Fractalkine/CX3CL1 was identified as a pSS protein signature as it could discern pSS from other autoimmune diseases." (PMID 35892673, 2022).
bone cancer (7 papers, 2014 to 2025). A primary or metastatic malignant neoplasm affecting the bone or articular cartilage. "The present study also suggested that activation of NF-κB signaling may underlie PAR2-mediated BDNF upregulation, central sensitization and behavioral hypersensitivity in the bone cancer pain." (PMID 24886294, 2014). "The phosphorylation of ERK/CREB pathway (pERK/pCREB) will be up-regulated with the aggravation of pain and pain aversion or exogenous injection of BDNF into rats suffering from bone cancer pain." (PMID 37008781, 2023). "Here, in the present study, a significantly increased BDNF in dorsal horn was revealed, and blocking BDNF signaling largely attenuated the enhanced glutamatergic strength and painful behavior in the rodent with bone cancer pain." (PMID 24886294, 2014). "Here, we investigated the expression of BDNF in the dorsal horn, and its functional significance in the bone cancer-induced pain." (PMID 24886294, 2014). "This suggested a critical involvement of BDNF in the spinal sensitization and hypersensitivity to painful stimuli in the bone cancer pain." (PMID 24886294, 2014). "Then, FSLLRY-NH2 (10 μg, from day3 to day 15), the antagonist of PAR2, was daily delivered via the intrathecal catheter to determine its effect on BDNF function, glutamatergic strength and pain behavior in the rats with bone cancer." (PMID 24886294, 2014). "The expression of BDNF was significantly increased in the dorsal horn of the rats with bone cancer pain." (PMID 24886294, 2014). "In bone tumors, BDNF can induce VEGF and enhance endothelial interactions, suggesting a route by which TrkB may contribute to vascular remodeling in mineralized tissues." (PMID 41567220, 2025). "This suggested a PAR2-mediated spinal BDNF upregulation in the setting of bone cancer pain." (PMID 24886294, 2014). "Among them, BDNF and TNF produced in bone tumor metastasis metabolism-α, MCP-1 and CCR2 can activate TRPA1." (PMID 35295475, 2021). "It has been suggested that BDNF is a key molecule in bone cancer pain, and the NGF-BDNF cascade reaction may be related to the occurrence of bone cancer pain." (PMID 39679363, 2024). "Blockade of NF-κB signaling by PDTC significantly reversed the upregulation of spinal BDNF in the rats with bone cancer-induced pain, while it did not obvious change the expression of spinal BDNF in the control rats." (PMID 24886294, 2014). "Currently, the role of BDNF in the induction and maintenance of enhanced spinal glutamatergic transmission has not been elucidated in the rodent model of bone cancer pain." (PMID 24886294, 2014). "In bone cancer pain, short-term exposure of cancer-related fibroblasts, MSCs, and osteoblasts to pH 6.8 can promote the expression of inflammatory and nociceptive mediators (NGF, BDNF, IL-6, IL-8, IL-1b, and CCL5), leading to nociceptor sensitization and hyperalgesia." (PMID 39679363, 2024). "Moreover, the present study demonstrated that inhibition the activity of either PAR2 or NF-κB largely attenuated the upregulation of BDNF in the dorsal horn, indicating that the PAR2 - NF-κB signaling critically participate in the spinal BDNF upregulation in the bone cancer pain." (PMID 24886294, 2014). "Significantly increased brain-derived neurotrophic factor (BDNF) expression was detected in the dorsal horn, and blockade of spinal BDNF signaling attenuated the enhancement of glutamatergic strength, thermal hyperalgesia and mechanical allodynia in the rats with bone cancer pain." (PMID 24886294, 2014).